IQGAP2 (IQ motif containing GTPase activating protein 2)
Diseases named in the same sentence as IQGAP2 in open-access papers (continued):
Sharing a sentence is not in itself a finding about the gene and the disease.
cancer (continued). "We observed that high frequency of mutations were present in IQGAP3 promoter but not in IQGAP2 promoter in different cancers." (PMID 29073199, 2017). "For instance, IQGAP2 was mostly downregulated in different cancer types viz." (PMID 29073199, 2017). "It would be interesting to prospect the opposing role of IQGAP2 in this particular cancer, wherein in-vitro studies could further help in identifying the role of IQGAP2 as a putative oncogene, along with IQGAP3." (PMID 29073199, 2017). "While IQGAP1 and IQGAP2 proteins share a domain structure and possess significant sequence homology, they appear to have opposing functions in vivo, at the very least in the pathogenesis of cancer." (PMID 22973521, 2012). "Additionally, IQGAP2 protein was absent from all samples in which the Iqgap2 promoter was hypermethylated, and a significant correlation was noted between Iqgap2 methylation and cancer aggressiveness." (PMID 20977743, 2010). "Interestingly, why IQGAP2 shows a reverse expression pattern in certain cancers viz." (PMID 29073199, 2017). "We found copy no. variation and mutations in specific cancers, for IQGAP2 and IQGAP3." (PMID 29073199, 2017). "We have summarized the current evidence on the contribution of IQGAP2 and IQGAP3 to these different types of cancer as examples." (PMID 36831467, 2023). "In this review, we summarize the different signaling pathways affected by IQGAP2 and IQGAP3, and the antithetic roles of IQGAP2 and IQGAP3 in different types of cancer." (PMID 36831467, 2023). "IQGAP2 inhibits epithelial-to-mesenchymal transition (EMT) and angiogenesis and promotes apoptosis in cancer cells." (PMID 36320006, 2022). "IQGAP1 plays a role in cancer progression, whereas IQGAP2 seems to act as atumor suppressor, and IQGAP3 promotes cancer growth and metastases." (PMID 29581849, 2018). "The percentage of each type of IQGAP2 and IQGAP3 genetic alteration with cancer type has been summarised in S5 Table." (PMID 29073199, 2017). "The mRNA expression of IQGAP2 and IQGAP3 in individual cancers were analysed in two different publicly available databases viz." (PMID 29073199, 2017). "To validate the in-silico analysis results we ascertained the expression and localization of IQGAP2 and IQGAP3 in cancer patients, using immunohistochemistry." (PMID 29073199, 2017). "For both IQGAP2 and IQGAP3, a weak correlation was observed between promoter methylation and subsequent gene expression in all cancer types." (PMID 29073199, 2017). "This will pave the way for using IQGAP2 and IQGAP3 as promising therapeutic targets and novel prognostic biomarkers for human carcinomas in the near future." (PMID 29073199, 2017). "Four of the down-regulated genes were known cancer genes: KAT2B (from the Ade sequence only), BCL2, IQGAP2 (from Ade & IBD), and PMT (from IBD only)." (PMID 23799036, 2013). "Here, we survey involvement of a significantly understudied protein, IQGAP2, and its homolog, IQGAP1, in cancer with more specific emphasis on the development of HCC." (PMID 22973521, 2012). "IQGAP2 expression correlated positively with survivability, on the contrary, IQGAP3 expression levels correlated inversely with survivability, in most of the cancers." (PMID 29073199, 2017). "However, only a few reports, in fewer sample size, are available which provide information regarding the expression pattern of IQGAP2 and IQGAP3 in different cancer types and their role in cancer development." (PMID 29073199, 2017). "Hence, IQGAP2 and IQGAP3 have potential to be used as prognostic markers or therapeutic targets in specific cancers." (PMID 29073199, 2017). "PKCε and PKA kinases regulate distinct signaling pathways, and while both have a role in cancer progression, their dissimilar activators and targets may also hold a key to deciphering the mechanisms behind the opposing functions of IQGAP1 and IQGAP2 in HCC." (PMID 22973521, 2012).
metabolic disease (1 paper, 2024). A congenital disorder (due to inherited enzyme abnormality) or acquired (due to failure of a metabolically important organ) disorder resulting from an abnormal metabolic process. "IQGAP2 is expressed in multiple organs and has been linked to the development of metabolic diseases and tumors." (PMID 38292407, 2024).
IQGAP2 also shares sentences with these, for which no sentence is quoted: glioma (3 papers); ameloblastoma (1); anaplastic oligodendroglioma (1); autism (1); autoimmune disease (1); brain ischemia (1); cardiac failure (1); cervical cancer (1); clear cell renal cell carcinoma (1); colon cancer (1); colon mucinous adenocarcinoma (1); diffuse astrocytoma (1); epilepsy (1); esophageal cancer (1); glaucoma (1); head and neck cancer (1); Hematochezia (1); infection (1); invasive ductal carcinoma (1); leukaemia (1); lung carcinoid tumor (1); lung papillary adenocarcinoma (1); lung squamous cell carcinoma (1); metastatic tumor (1); oligoastrocytoma (1); oligodendroglioma (1); prostate tumor (1); rectal adenocarcinoma (1); rectal mucinous adenocarcinoma (1); skeletal system disease (1).
A further 3 diseases each share a sentence with IQGAP2 in 1 paper.